EGFR (epidermal growth factor receptor)
Diseases named in the same sentence as EGFR in open-access papers (continued):
Sharing a sentence is not in itself a finding about the gene and the disease.
cancer (continued). "In addition to miRNA, the specific expression of cancer markers CD24, survivin, focal adhesion kinase (FAK), and epidermal growth factor receptor (EGFR) in BC-derived exosomes may be considered biomarkers for BC metastasis." (PMID 37153744, 2023). "Considering that the ERBB family member ERBB3 was reported to recruit PI3Kβ and thereby drive PI3Kα inhibitor resistance in HER2‐amplified and PIK3CA mutant cancers, we hypothesized that ALK inhibition may similarly activate EGFR and thereby regulate PI3Kβ function." (PMID 36423211, 2023). "Fourth, we did not sent the cancer tissues before EGFR‐TKI treatment for NGS." (PMID 38140788, 2023). "Developing evidence suggests that IL-33 may regulate the immune response through a signaling complex between IL-33R and EGFR in gastrointestinal helminth infections; however, we are not aware of current research supporting this pathway in cancer." (PMID 37511453, 2023). "Therefore, searching small molecular inhibitors which can target both EGFR and AKT may help cancer treatment." (PMID 38005329, 2023). "More recently, a LDCT screening study for primarily non-smoking Asian women, the demographic commonly associated with EGFR mutant LUAD, found an increase in cancer incidence in early-stage cancers (stages 0-I) yet no change in late-stage incidence (stages II-IV)." (PMID 38260835, 2023). "Our results showed that PD13 could potentially act as a promising non-mutant and mutant EGFR drug for cancer therapy." (PMID 37049777, 2023). "Therefore, a positive feedback loop may exist between the EGFR/MEK/MAPK pathway and IGF2BP3 expression in cancer cells." (PMID 37658049, 2023). "Additionally, exosomal EGFR can activate the AKT and MAPK signaling pathway to human umbilical vein endothelial cells (HUVECs) by conveying cancer cell-derived EGFR signals, which is accomplished via the presentation of intact EGFR kinase activity and phosphatidylserine (PS)." (PMID 36834471, 2023). "Thus, the combination of two agents demonstrates an enhanced effect of anti-cancer activity in which 5-Aza-induced upregulations MUC17 and MZF1 may promote the sensitivity of NSCLC resistant cells to EGFR-TKIs." (PMID 36778111, 2023). "However, not all patients with tumors expressing high levels of EGFR respond to these drugs, and many cancers develop resistance to such treatments." (PMID 37626832, 2023). "These, in turn, can reactivate dormant DTC proliferation, renew CD133+ cancer cells and endocrine resistance by IL-6/Notch signaling through the IL-6 receptor gp130/gp80 and activated STAT3, through VEGF via PI3K/Akt signaling, SMAD2 and 3, and the EGFR and ERK pathways." (PMID 37296983, 2023). "We speculated that these failures are related to the heterogeneity of TNBC, and that the EGFR signaling pathway might not act as a driver of cancer per se." (PMID 36737605, 2023). "This is because the extent of expression might not designate the extent to which cancer, or the cancer cell line, is reliant on EGFR signals for growth." (PMID 38090376, 2023). "EGFR-targeted therapies, such as cetuximab and panitumumab, may also affect neighboring stromal cells near the cancer cells, promoting an increase in the secretion of EGF, inducing resistance against EGFR-targeted therapies through continuous mitogen-activated protein kinase (MAPK) signaling." (PMID 37296986, 2023). "The majority of EGFR positive cancers do not respond to TKIs or to mAb." (PMID 37170144, 2023). "All patients had never received prior EGFR TKIs or cytotoxic drugs for anti-cancer treatment." (PMID 36910673, 2023). "EGFR induction of TF, a prothrombotic receptor and cofactor for factor VII/VIIa in the coagulation cascade, has also been hypothesized to increase thrombosis with malignancies." (PMID 37232831, 2023). "Moreover, EGFR performs functions that are independent of its tyrosine kinase activity in cancer cells which necessitate new perspectives in assessing EGFR for cancer management." (PMID 37114127, 2023).
cancer (continued). "As H460 cells are EGFR wild-type cells, the results mean that the activation of phosphorylated proteins of AKT, ERK and JNK were existed in the cancer cells and suppressed by the combination agents, which might be responsible for the synergistic effect of HCPT and CRI on H460 cells." (PMID 36305251, 2023). "The evidence that this gene co-amplification occurs in different human cancers could suggest a functional relationship between CBX3, EGFR and RAC1 genes which normally occurs in physiological conditions but that could promote cancer progression when dysregulated." (PMID 37633946, 2023). "In addition, the expression of granzyme B (GZMB) and genes involved in CD8+ TRM cell activation has been shown to be lower with EGFR-MT than the wild type, indicating that CD8+ TRM cells in EGFR-MT tumors have a lower anti-neoplastic activity to kill cancer cells." (PMID 36949948, 2023). "Additionally, NKG2D ligands in cancer cells correlated positively with the activation of EGFR and its downstream MEK pathway, which is commonly hyperactivated in those tumors and reduced by EGFR inhibitors." (PMID 37601668, 2023). "For example, this platform, without any modification, could be useful for other cancers that overexpress EGFR." (PMID 37514162, 2023). "In addition to the AKT pathway, other signaling pathways have also been reported to be involved in PDIA3-mediated biological functions in cancers, such as STAT3 signaling, EGFR signaling, 1alpha, 25-dihydroxy vitamin D3 [1,25(OH)2D3]-mediated pathway and mTOR signaling." (PMID 38213579, 2023). "Last, but not least, blocking EGFR palmitoylation (mutation of Cys797, Cys1025, and Cys1122 to alanine) disrupted TKI‐induced EGFR dimerization, resulting in the apoptosis of TKI‐resistant cancer cells." (PMID 36018061, 2023). "We next addressed whether driver mutations existed at other genomic loci in EGFR and in KRAS using an independent ultradeep sequencing platform in a separate group of patients with and without cancer (n = 81)." (PMID 37020004, 2023). "Additionally, 17β-estradiol (E2) activates EGFR, thus stimulating the MEK1/2 and PI3K pathways and further increasing the expression of CIP2A/p90 through the MEK1/2-induced transcription factor Ets1 to enhance the proliferation of cancer cells." (PMID 36911405, 2023). "Cholesterol’s role in lipid rafts and caveolae in the plasma membrane may impact cancer cell proliferation and survival via effects on signaling by receptors such as HER2, EGFR and CXCR4, as well as transducers and effectors such as PI3K, SRC family kinases and NOX, along with other regulators." (PMID 37568764, 2023). "In contrast, none of the four metaplastic carcinomas in this study had EGFR alteration." (PMID 38201434, 2023). "The use of EgB4 may thus help identify specific types of cancers that are characterized by the presence of EGFR or EGFRvII rather than EGFRvIII, and therefore provide useful insight into the type of cancer." (PMID 35232398, 2022). "While both EMT and ZEB1 has been found to medicate acquired resistance to EGFR inhibitors in non-small cell lung cancer, our iGenSig signature suggested the discordance of ZEB1 overexpression with EMT induction and their differential contribution to Erlotinib resistance in Pan-cancer cell lines." (PMID 35618721, 2022). "It is known that EGFR is overexpressed in cancer cells but not normal cells." (PMID 35999506, 2022). "Surprisingly, it also did not affect MCF-7 and HepG2 which are EGFR-negative cancer cells." (PMID 35578244, 2022). "Furthermore, antibodies against the epidermal growth factor receptor (EGFR) could be incorporated on the LNP surface to promote receptor mediated endocytosis of LNPs and the release of mRNA cargo in cancer cells." (PMID 35393569, 2022).
cancer (continued). "The NBSNe conjugate (i) was efficiently uptaken by cancer cells and generated ROS upon irradiation due to the presence of the NBS, resulting in robust phototoxicity, and (ii) significantly inhibited cell migration and invasion due to the action of the EGFR inhibitor (Ne)." (PMID 35213974, 2022). "These include anti-EGFR monoclonal antibodies for KRAS wild type disease, combinations of anti-EGFR monoclonal antibodies with BRAF inhibitors for BRAF mutant cancers, anti-HER2 therapies for HER2 altered cancers and immune checkpoint inhibitors for microsatellite instability (MSI) high cancers." (PMID 36295658, 2022). "The two GPER targets (EGFR and PI3K) are activators or initiators of downstream signaling pathways and thus, could serve as primary foci in the GPER-mediated therapy for most of the cancers we studied and for some diabetic conditions." (PMID 36558071, 2022). "Our data show that left-sided CRC cancer cells exhibited significantly stronger EGFR signaling, VEGF signaling, and ErbB signaling than right-sided CRC cells, which is consistent with our clinical findings that left-sided CRC is more sensitive to monoclonal antibodies against EGFR, VEGF and ErbB." (PMID 34793335, 2022). "By performing a combined analysis of cancer cell line dependency data from DepMap and the CCLE transcriptomic data of 1000 cell lines of 22 origins, we have clustered cell types according to their dependency on EGFR knockout and the expression of 16 genes listed in methionine metabolism KEGG." (PMID 36361596, 2022). "Both mechanisms of cancer growth and metastasis are regulated by a large panel of circulating activators from several neuropeptides to membrane-bound factors released by matrix metalloprotease (MMP)-dependent shedding, such as Epidermal Growth Factor Receptor (EGFR) ligands." (PMID 36233189, 2022). "In addition, EGFR and HER2 have been validated as rational targets for cancer-related treatment." (PMID 36678540, 2022). "Markers like EGFR and HER2 are clinically important targets in cancer treatment but might either be missed (if their surface expression is underestimated based on a limited biopsy) or lose their potential as a successful treatment target (if their expression changes with treatment)." (PMID 35145836, 2022). "Indeed, several studies implicate CIC in the sensitivity to EGFR and MAPK pathway inhibitors, suggesting that CIC may play a broader role in human cancer than originally anticipated." (PMID 36358827, 2022). "Lastly, KRT1high BLCA patients had significantly higher expression of EGFR and MKI67, suggesting that proliferation is potentiated in this group; this complements the survival analysis (high KRT1 is unfavorable in BLCA) and IHC data (KRT1 staining is higher in cancer than normal specimens)." (PMID 35361846, 2022). "However, despite a high expression level of EGFR, a subset of cancers did not respond to anti-EGFR treatment." (PMID 35455447, 2022). "It acts as a negative feedback regulator of EGFR signaling in human malignant tumors." (PMID 34845855, 2022). "Interestingly, this increase in cancer cell migration could be inhibited by combined treatment with VEGFR2 and EGFR antibodies, as was demonstrated by a decreased migration of glioblastoma cells in an in vitro system." (PMID 36119528, 2022). "As a result, the therapeutic index, which is the ratio of IT doses that cause toxic versus therapeutic effects, or the therapeutic window, which is the range of IT dosages that can effectively treat cancer without exerting toxic effects, of anti-EGFR ITs should be improved further." (PMID 36555466, 2022). "Previously, we have shown that composites of antisense oligonucleotide and boron clusters are functional nanoparticles for the downregulation of expression of epidermal growth factor receptor (EGFR) and can be loaded into EGFR-overexpressing cancer cells without a transfection factor." (PMID 36499115, 2022).
cancer (continued). "A cytotoxic compound derived from the EGFR TK inhibitorerlotinib was synthesized to allow further conjugation to the surfaceof LNO HNPs displaying surface-reactive azide functionalities, whilepreserving the growth inhibitory effect of the parent drug moleculeon human prostate DU145 cancer cells." (PMID 35996436, 2022). "The invasion of cancer cells to the perivascular environment relies on their motility, in which motility-involving molecules such as ARP2/3, L1CAM, serpins, CD44, CDC42, CXCR4, epidermal growth factor receptor (EGFR), as well as Wnt7 signaling, are critical players." (PMID 36119528, 2022). "According to research, which showed that EGFR activation in various cancer cell lines was α2-6 sialylation-dependent, ST6Gal-I OE in Suit2 cells increased α2-6 sialylation and basal EGFR activation, whereas ST6Gal-I KD in S2-013 and S2-LM7AA decreased EGFR sialylation and activation." (PMID 36547200, 2022). "Additionally, the combined targeted therapy, including targeted agents (which were against EGFR, ALK, BRAF, IGF-1R, MET(c-MET), VEGF) and antibody–drug conjugate (ADC), as well as cancer vaccines, was among the top three most effective treatment interventions in this study." (PMID 36361201, 2022). "Our data demonstrate that initiating genetic events (EGFR-mut, KRAS-mut or variable in NEK) influence the subsequent pattern of stabilizing and directional selection on other genes and molecular pathways consistent with driver-dependent coadapted syndromes for each cancer type." (PMID 36612014, 2022). "The proteoglycans in cancer pathway (ecb05205) regulates proteoglycans in the extracellular matrix, which influences the behavior of cancer cells and their microenvironment by interacting with various cytokines (e.g., TWIST2), growth factors (e.g., HGF) and cell surface receptors (e.g., EGFR)." (PMID 36553455, 2022). "As an example, work in wtEGFR-expressing cancer cells highly resistant to EGFR-TKIs (Hela-R30 and OSCC 686LN), in which autophagy is not robustly activated, showed that rapamycin, an mTOR inhibitor, both restored autophagy in these cells and augmented the cytotoxic effect of EGFR-TKIs." (PMID 35158954, 2022). "EGFR-Tyrosine Kinase Inhibitors (TKIs) strengthen MHC class I and II antigen presentation in response to IFN-γ, boost CD8+ T-cells levels and DCs, eliminate FOXP3+ Tregs, inhibit macrophage polarization into the M2 phenotype, and decrease PD-L1 expression in cancer cells." (PMID 35742933, 2022). "Moreover, in EGFR-mutated cancers, the non-inflamed immunosuppressive TME (high levels of Tregs and low levels of CD8+ T cells) diminishes the expression of EGFR by Tregs, leading to the development of the resistance to TKIs." (PMID 35742933, 2022). "The abnormally high expression of RPN2 in a variety of cancer subtypes plays an important role in the drug resistance and invasion progression of cancer cells by regulating the N-terminal glycosylation of various proteins such as p-glycoprotein, CD63, and epidermal growth factor receptor (EGFR)." (PMID 35265520, 2022). "EGFR lacking the fourth exon after AS can consistently activate the proliferation of cancer cells." (PMID 36591484, 2022). "Firstly, the results obtained for the complete group of ALK/EGFR-negative tumors stayed correct for the subgroup of treatment-naïve tumors: Tregs were higher in ALK-positive cancer compared to treatment-naïve ALK/EGFR-negative cancer (FC = 2.3, p = 0.00015)." (PMID 34125345, 2022).
cancer (continued). "Pretreatment of cancer cells with actinomycin D, a transcription inhibitor, almost abolished EGF-enhanced HIF-1α expression in GSCs, LN229, and U251 cells, suggesting that transcriptional regulation of HIF-1α is essentially involved in response to EGFR activation." (PMID 36435833, 2022). "DHA and EPA may be potential EGFR antagonists; they exert antiproliferative effects by inhibiting the EGFR pathway in cancer cells but not in normal cells 27,28." (PMID 36483592, 2022). "While exhibiting both mutations in a single cell may be selected against, it does not mean that an EGFR mutant cancer cell would be at a disadvantage in a community of KRAS-mutant cancer cells and vice-versa." (PMID 35061724, 2022). "The findings provide evidence for the notion that some cells may rely on TGF-induced EGFR activation and promote IL-8 production and, thus, together with VEGF, stimulate the formation of new blood vessels to enhance the survival of cancer cells and promote their metastatic potential." (PMID 35409206, 2022). "Finally, the activation of signal pathways related to Epidermal Growth Factor Receptor (EGFR), Focal Adhesion Kinase (FAK), and NF-κB exerts several activities to provide protection against CDDP-related death signals in OSCC cancer cells and are commonly reported in this subgroup of patients." (PMID 36613780, 2022). "EGFR may be transactivated by GPCRs for regulating DNA expression and the cell cycle, as well as by LPA and S1P for mediating cancer pathophysiology." (PMID 36601056, 2022). "Furthermore, EGFR/STAT3 pathway promotes and maintains cancer stemness." (PMID 35681787, 2022). "Activation of receptor tyrosine kinases, such as the epidermal growth factor receptor (EGFR) and human epidermal growth factor receptor 2 (HER2), leads to increased mTOR activity and increased HIF-1α mRNA translation into protein in prostate and breast cancer, respectively." (PMID 35642641, 2022). "In addition, EVs containing secretory epidermal growth factor receptor (EGFR) derived from GC cells effectively activate hepatocyte growth factor, which in turn binds to c-MET receptors on migrating cancer cells to promote the homing of metastatic cancer cells." (PMID 35886934, 2022). "However, EGFR-Lipo-CPT-11 exhibited the strongest effect in SW620 high EGFR-expressed cell lines, showing that the PEG-loaded CPT-11 specifically targets EGFR-expressing cancer cells." (PMID 35918704, 2022). "Notably, transcripts for PD-1 (Pdcd1) were observed only in T cell clusters whereas PD-L1 (Cd274) transcripts were more abundant in neutrophils, DCs and macrophages and PD-L2 (Pdcd1lg2) in DCs and not in EGFR+ cancer cells." (PMID 35624211, 2022). "The in vitro studies showed that our optimized DTPA-derivatized NMs were able to perfectly protect the formulated siRNA and preserve their active targeting properties, as reflected by a 1.7-fold higher siRNA transfection efficiency level in EGFR-positive cancer cells compared to non-targeted NMs." (PMID 36559172, 2022). "Consistent with our prior studies showing α2-6 sialylation-dependent EGFR activation in other cancer cell lines, ST6Gal-I OE in Suit2 cells increased the α2-6 sialylation and basal activation of EGFR, whereas ST6Gal-I KD in S2-013 and S2-LM7AA diminished EGFR sialylation and activation." (PMID 33148698, 2021). "Therefore, we compared the specific targeting potential of cetuximab (an anti-EGFR antibody) functionalised AuNR in both EGFR-positive and -negative cancer cell lines and evaluated in vitro the therapeutic potential of PTT in aggressive HNSCC cells." (PMID 34683944, 2021). "Having identified EGFR as a promising molecular target in feline oral carcinoma, we first confirmed the presence of membrane EGFR on three feline OSCC cell lines (SCCF1, SCCF2, and SCCF3), in comparison to two well-characterized human cancer cell lines (HeLa and MCF7)." (PMID 36405501, 2021).